TRH (thyrotropin releasing hormone)
Diseases named in the same sentence as TRH in open-access papers (continued):
Sharing a sentence is not in itself a finding about the gene and the disease.
Central hypothyroidism (continued). "Heterozygous carriers of pathogenic TRHR variants with a mild effect on TRH resistance may have an elevated serum TSH; on the other hand, isolated TSH elevation instead of central hypothyroidism has been reported in homozygous carriers." (PMID 34566885, 2021). "Therefore, roxadustat may cause central hypothyroidism due to suppressing thyroid-stimulating hormone (TSH) release in the pituitary gland and/or thyrotropin-releasing hormone release in the hypothalamus." (PMID 39872568, 2024). "TRH stimulation test can be used in the differential diagnosis of inappropriate TSH secretion (thyrotropinoma and thyroid hormone resistance), central hypothyroidism, hyperprolactinemia and in the diagnosis and prognosis of acromegaly." (PMID 39037546, 2024). "Less TRH is produced when the hypothalamus is injured, which decreases the release of TSH, Triiodothyronine (T3), and T4, resulting in central hypothyroidism." (PMID 36389395, 2022). "Although whole hypothalamic-pituitary axis function assessment is indispensable to identify combined pituitary hormone deficiencies, a TRH test is not essential and could not rule out central hypothyroidism, and the diagnosis should be made by regular thyroid hormone monitoring." (PMID 35488223, 2022). "Therefore, roxadustat can lead to central hypothyroidism by inhibiting the release of thyroid-stimulating hormone (TSH) from the pituitary gland and/or thyrotropin-releasing hormone from the hypothalamus." (PMID 39872568, 2024). "Central hypothyroidism (CH) was diagnosed due to low free thyroxine level and normal or mildly elevated TSH levels at the baseline, although the TSH level responded normally to thyrotropin-releasing hormone (TRH) stimulation." (PMID 37231428, 2023). "Neither serum triiodothyronine (FT3) level nor the thyrotropin-releasing hormone (TRH) test is considered a reliable test of central hypothyroidism." (PMID 31011999, 2019). "A thyrotropin-releasing hormone (TRH) stimulation test performed on day 21 of admission reveled low release of TSH under conditions of low serum FT3 and FT4 levels, confirming the diagnosis of central hypothyroidism." (PMID 28835258, 2017). "In a study of 54 children with central hypothyroidism, 23.3% had a normal TRH test, only 30% had an absent or blunted TSH response suggestive of pituitary disease, whilst 30% had a delayed hypothalamic response and 16.7% a brisk response." (PMID 26416826, 2015). "In addition to the declined growth at presentation, central hypothyroidism and blunted TRH test, no other phenotypic alterations were found." (PMID 34093435, 2021). "However, more recent studies in children with central hypothyroidism suggest that TRH testing has both a poor negative predictive value, and an inability to distinguish between hypothalamic and pituitary defects." (PMID 26416826, 2015).
hyperprolactinemia (28 papers, 2011 to 2025). Abnormally high level of prolactin in the blood. "This is supported by the data for therapy by the dopamine receptor blockers leading to subclinical hypothyroidism and hyperprolactinemia that causes the elevation of TRH." (PMID 36747015, 2023). "Supporting the pituitary origin of the hormonal deficiency in Case 1, mild hyperprolactinemia, usually seen in pituitary defects and secondary to the hypothalamic thyrotropin-releasing hormone (TRH) stimulation, was detected." (PMID 25260871, 2014). "Physicians should be aware of hyperprolactinemia-associated side effects in patients receiving thyrotropin-releasing hormone treatment." (PMID 22152284, 2011). "Physicians should be cognizant of hyperprolactinemia-associated side effects in patients receiving TRH treatment." (PMID 22152284, 2011). "Given the results of the in vitro experiment, it was expected that long-term treatment with TRH would cause hyperprolactinemia." (PMID 22152284, 2011). "It has been reported that hyperprolactinemia is associated with pituitary stalk compression due to pituitary enlargement‐induced disruption of hypothalamic inhibition, or thyrotropin‐releasing hormone (TRH)‐related hyperprolactinemia." (PMID 41321897, 2025). "Elevated TRH levels drive thyrotroph hyperplasia while concurrently stimulating lactotroph expansion, which results in hyperprolactinemia." (PMID 40893882, 2025). "Increased TRH production stimulates both thyrotrophic and lactotrophic pituitary cells, resulting in pituitary enlargement and hyperprolactinemia (due to the cross-sensitivity between TSH and prolactin-producing pituitary cells to TRH stimulation)." (PMID 39015673, 2024). "But some of the studies investigated TRH stimulation test in other disorders such as hyperprolactinemia, other pituitary disorders or sellar mass lesions or as a combined test for hypopituitarism." (PMID 38700812, 2024). "In primary hypothyroidism, the release of a negative feedback regulation can lead to increased hypothalamic TRH secretion, resulting in hyperprolactinemia." (PMID 35892862, 2022). "Then, by observing the release of prolactin, hyperprolactinemia was examined 15 min and 30 min after the intravenous injection of 200 μg Thyrotropin-releasing hormone (TRH)." (PMID 35893648, 2022). "Hormonal causes most frequently associated with galactorrhea are hyperprolactinemia and thyroid conditions with elevated levels of TSH or TRH hormones." (PMID 23456048, 2013). "Another possible reason for the FSH and LH mismatch is that high TRH can induce hyperprolactinemia which also can impair LH pulse by intermittent reductions in GnRH secretion." (PMID 21861901, 2011). "Our patient had a normal PRL level but showed a response pattern suggestive of latent hyperprolactinemia following stimulation with TRH." (PMID 22152284, 2011). "Although the basal secretion level of PRL was within the normal range, an over-response in PRL secretion was noted in the TRH provocation test, suggesting latent hyperprolactinemia." (PMID 22152284, 2011). "Moreover, TRH also has a weak stimulatory effect on lactotroph cells, responsible of the state of hyperprolactinemia (lactotroph hyperplasia) as also observed in our patients." (PMID 38650008, 2024). "Hyperprolactinemia is a common feature in children with this syndrome and is TRH-mediated." (PMID 39015673, 2024). "For example, even for a more stable analog of TRH as Taltirelin, hyperprolactinemia is induced." (PMID 32457627, 2020). "Triclosan in mice was found to reduce the production of TRH and thyroid-stimulating hormone (TSH), and this decreased effect could further cause hyperprolactinemia." (PMID 32010181, 2019). "Because TRH also has a weak stimulatory effect on lactotroph cells, mild to moderate hyperprolactinemia may also occur in about three-quarters of patients." (PMID 21473748, 2011).
hyperprolactinemia (continued). "Given that a hormone provocation test showed a marked increase in the PRL level from 7.1 ng/mL before provocation to 142.7 ng/mL 30 minutes after provocation with TRH, our patient was considered to have latent hyperprolactinemia with abnormal lactation and menstruation." (PMID 22152284, 2011). "Therefore, at the initial presentation of our patient to our hospital, we speculated that the excessive dosing of TRH might have induced hyperprolactinemia and subsequent amenorrhea." (PMID 22152284, 2011). "The direct correlation between serum TSH and prolactin levels suggests that hyperprolactinemia in primary hypothyroidism is primarily mediated by thyrotropin-releasing hormone release in the absence of negative feedback from T3 and T4." (PMID 39416273, 2024). "In addition, since thyrotropin-releasing hormone (TRH) acts as a stimulating factor for PRL, prolonged primary hypothyroidism may result in a stimulus on the hypothalamic–pituitary–thyroid axis with consequent hyperprolactinemia." (PMID 34207687, 2021).
Primary hypothyroidism (20 papers, 2012 to 2025). A type of hypothyroidism that results from a defect in the thyroid gland. "Primary hypothyroidism is characterized by a loss of thyroxine feedback inhibition and an increase in thyrotropin-releasing hormone (TRH) levels, resulting in reactive pituitary hyperplasia." (PMID 40893882, 2025). "The loss of thyroxin feedback inhibition in primary hypothyroidism causes overproduction of thyrotropin-releasing-hormone (TRH), which results in secondary pituitary enlargement." (PMID 27199892, 2016). "Primary hypothyroidism is characterized by loss of thyroxine feedback inhibition and overproduction of thyrotropin-releasing hormone, which might result in reactive pituitary hyperplasia." (PMID 32080117, 2020). "Primary hypothyroidism hinders regulation of the HPO axis since excessive TRH secretion will interfere with GnRH pulsatility." (PMID 30621143, 2019). "Primary hypothyroidism leads to increased thyrotropin-releasing hormone (TRH) release from hypothalamus, which has a physiologic trophic effect on thyrotrophs and lactotrophs resulting in increased TSH and prolactin levels, respectively." (PMID 28529200, 2017). "TRH test revealed normal results in four infants, while sixteen infants had exaggerated response suggestive of primary hypothyroidism." (PMID 26831555, 2015). "In long-standing primary hypothyroidism, insufficient production of thyroid hormones directly or indirectly leads to overproduction of TSH and thyrotropin-releasing hormone (TRH) due to the loss of thyroxine feedback inhibition." (PMID 26421010, 2015). "In some cases, the extremely elevated thyrotropin-releasing hormone levels seen in prolonged primary hypothyroidism can lead to the rare finding of anterior pituitary enlargement (pseudotumor of the pituitary gland)." (PMID 23725039, 2013). "The lack of thyroxine feedback found in uncontrolled primary hypothyroidism leads to elevated levels of TRH which causes both pituitary thyrotroph and lactotroph hypertrophy, increasing the secretion of both TSH and prolactin." (PMID 23133775, 2012). "If primary hypothyroidism is not detected and treated promptly, chronic TRH drive producing increased TSH secretion can lead to pituitary hyperplasia mimicking a pituitary adenoma." (PMID 41257121, 2025). "In primary hypothyroidism, low levels of thyroid hormone reduce hypothalamic negative feedback, leading to TRH hypersecretion." (PMID 40893882, 2025). "Furthermore, there is a recent case report about BAT visualization on FDG-PET/CT in severe primary hypothyroidism that suggested a potential role of TSH and TRH as regulators of BAT activation." (PMID 29666563, 2018). "In primary hypothyroidism, low levels of thyroid hormones diminish negative feedback inhibition on the hypothalamus, leading to excessive secretion of thyrotropin-releasing hormone (TRH) and subsequent thyrotropic hyperplasia." (PMID 40893882, 2025). "Serum TSH was elevated after administration of pharmacological doses of thyrotropin-releasing hormone (TRH) to patients with subclinical and overt primary hypothyroidism, but TRH treatment did not influence the amount of sialylated or terminally galactosylated TSH isoforms." (PMID 30227620, 2018).
hyperthyroidism (18 papers, 2011 to 2025). Overactivity of the thyroid gland resulting in overproduction of thyroid hormone and increased metabolic rate. "Thyrotropin releasing hormone is one of the hormones that regulate the level of serum thyroid hormone in a certain range, so the mutated gene can affect the incidence of hyperthyroidism by affecting the secretion of these hormones." (PMID 37876543, 2023). "In prolactinoma and active hyperthyroidism, the prolactin response to the TRH stimulation test is significantly blunted." (PMID 39037546, 2024). "The increase in TSH response to TRH has been recognized, having a direct effect on the thyroid gland resulting in hyperthyroidism." (PMID 33995058, 2021). "Local hyperthyroidism in the hypothalamus suppresses TRH release, which helps avoid excessive TRH response that could affect the body’s adaptability to fasting." (PMID 39253586, 2024). "Therefore, in patients taking exogenous T3, the body will sense a hyperthyroidism state and shut down the secretion of thyrotropin-releasing hormone, TSH, and T4 as seen in our case." (PMID 31799099, 2019). "Also, the importance of TRH for the significant and long-lasting release of endogenous acetylcholine in the hippocampus and the increased acetylcholinesterase activity in hyperthyroidism remind us of the importance of hyperthyroidism on the metabolism of acetylcholine." (PMID 38419953, 2024). "However, there was no causal relationship between GD, hyperthyroidism, TC, TSH, TRH, TBG, THRα, TP, TG, and AA." (PMID 39205687, 2024). "Non-suppressed TSH level, abnormal response to TRH stimulation, and a high alpha-subunit/TSH molar ratio are some biochemical tests that can aid in identifying concomitant TSHoma in a patient with hyperthyroidism who is being worked up for GD." (PMID 38311752, 2024).
thyroid (11 papers, 2012 to 2023). "In non-thyroidal diseases, low T3 syndrome is the most common type, and severe infections such as sepsis can lead to insufficient secretion of thyrotropin-releasing hormone (TRH) and thyroid-stimulating hormone (TSH) due to inflammatory cytokines." (PMID 35634497, 2022). "First, the time course of the elevation of the rat prepro-TRH mRNA after the administration of an anti-thyroid drug, precisely correlates with that of TSHβ mRNA." (PMID 33201916, 2020). "In pathophysiological conditions such as thyroid disorder, vasoactive intestinal polypeptide stimulates PRL synthesis and thyrotropin-releasing hormone increases secretion; in renal impairment, it decreases PRL clearance and increases serum PRL levels." (PMID 35339194, 2022). "Thyroid nodules become autonomous and produce thyroid hormones independent of signals from either TSH or thyrotropin-releasing hormone (TRH)." (PMID 31655515, 2019). "To this end, we examined articles present in the PubMed database by entering the following keywords in the advanced search builder: colorectal cancer; thyroid disease; colorectal cancer AND thyroid disease/hypothyroidism/hyperthyroidism/thyroid cancer/thyroid hormones/TSH/TRH." (PMID 36983233, 2023). "In the 1980s, the first studies of FHT associated such a disease with a primary thyroid gland abnormality rather than with the effect of circulating TSH, or thyrotropin-releasing hormone (TRH)." (PMID 34573128, 2021). "Various thyroid abnormalities, including a low response of serum TSH to a thyrotropin-releasing hormone (TRH) stimulation test, impaired production of thyroxine (T4) by the thyroid gland and lower free triiodothyronine (fT3) serum levels, mainly in KS adults, but also in KS children, were described." (PMID 33557156, 2021). "When thyroid abnormalities exist, they consist mainly of elevated T4 levels, low T3, elevated rT3, blunted TSH response to TRH, positive antithyroid antibodies, and elevated cerebrospinal fluid (CSF) TRH concentrations." (PMID 22220285, 2012).
pituitary adenoma (10 papers, 2011 to 2025). "It was reported that patients with GH-producing pituitary adenomas and a tumor-stimulatory G protein (gsp) mutation had small tumor volume with a higher rate of TRH responders, which provided a theoretical background for inverse correlation between the GH response to TRH and tumor volume." (PMID 24348552, 2013). "A total of 359 individual TRH tests were performed, giving rise to a representative cohort of a wide range of pituitary adenoma cases." (PMID 37850100, 2023). "TRH stimulation test revealed that it was less likely due to either RTH or TSH secreting pituitary adenoma for inappropriately increased TSH." (PMID 29973617, 2018). "This paradoxical response of GH to thyrotropin-releasing hormone (TRH) in GH-producing pituitary adenomas was first reported in 1972 and observed in 50~75% of untreated acromegalic patients." (PMID 24348552, 2013). "The present study investigated the relationship between the volume of GH-producing pituitary adenomas and their responsiveness to TRH." (PMID 24348552, 2013). "Locally released TRH produced by pituitary adenomas could act as an autocrine and/or paracrine regulator to affect hormone release or tumor growth." (PMID 24348552, 2013). "The response was normal, with TSH increasing more than 50% after TRH stimulation, and the diagnosis of TSH-secreting pituitary adenomas was excluded." (PMID 36499571, 2022). "Altogether, these results showed that responsiveness to TRH during the TST in GH-producing pituitary adenomas was not inversely correlated with tumor volume." (PMID 24348552, 2013). "Moreover, few studies have explored the relationship between responsiveness to TRH during the TST and tumor volume in GH-producing pituitary adenomas." (PMID 24348552, 2013). "A decrease in thyroid hormones reduces negative feedback, leading to elevated TRH; if prolonged, this can result in persistent elevation in TRH levels and pituitary hyperplasia, which may be misinterpreted as pituitary adenoma." (PMID 41257121, 2025). "In order to rule out TSH-secreting pituitary adenomas, the TRH stimulation test was done." (PMID 36499571, 2022). "The T3 suppression test is used for diagnosis and excluding non-functioning pituitary adenomas, but it is not necessary if a macroadenoma is found on MRI along with high FT4, normal TSH, and abnormal TRH stimulation test." (PMID 38642582, 2024). "In the thyrotropin-releasing hormone load test, TSH did not increase at all, which was also compatible with TSH-secreting pituitary adenoma." (PMID 34967378, 2021). "Further studies demonstrated the absence of a pituitary adenoma and the rise in TSH following the injection of TRH." (PMID 21871106, 2011).
cerebellar ataxia (9 papers, 2012 to 2024). A neurological syndrome characterized by clumsy and uncoordinated movement of the limbs, trunk, and cranial muscles. "More importantly, intravenous administration of TRH for two weeks significantly improves clinically evaluated cerebellar ataxia in patients with spinocerebellar degeneration, particularly in lessening dysmetria." (PMID 38397008, 2024). "Recently, a few attempts of pharmacological treatments have been performed in patients of mixed groups of dominant and recessive ataxias, showing some weak and short-lasting benefit with riluzole and thyrotropin releasing hormone." (PMID 35933444, 2022). "The TRH analog C-Trelin orally disintegrated (OD) tab has been proposed for the treatment of spinocerebellar degeneration, including SCA3, and a Phase 4 trial was registered in 2019 (NCT04107740)." (PMID 32357546, 2020). "A synthetic TRH analog, taltirelin, was shown to ameliorate ataxic behavior in the hereditary rolling mouse Nagoya, a murine model of spinocerebellar ataxia." (PMID 30618637, 2018). "Taltirelin hydrate (10 mg/day), which is a thyrotropin-releasing hormone analog used in Japan for the treatment of spinocerebellar degeneration, was administered to 10 patients." (PMID 23116490, 2012). "In addition, TRH receptor agonists also significantly ameliorate 3-AP-induced cerebellar ataxia in rats, and the effect of TRH is completely counteracted by NMDA receptor antagonists." (PMID 38397008, 2024). "In the clinic, TRH has been used as a treatment for cerebellar ataxias." (PMID 38397008, 2024). "A Phase 3 trial in 2013 (NCT01970098) found that the TRH derivative rovatirelin (KPS-0373) improved severe ataxia in SCA31 and SCA6 patients and that these effects were more prominent than in patients with less severe ataxia." (PMID 32357546, 2020). "However, the mechanisms by which TRH and taltirelin mitigate cerebellar ataxia have not yet been fully clarified." (PMID 30618637, 2018).